IL1B (interleukin 1 beta)
Diseases named in the same sentence as IL1B in open-access papers (continued):
Sharing a sentence is not in itself a finding about the gene and the disease.
pneumonia (continued). "We demonstrated in vivo that the presence of PVL was associated with an increase in IL-1β levels in the BALF of infected rabbits, thus highlighting the relevance of this pathway during pneumonia." (PMID 24905099, 2014). "The concentrations of the cytokines interleukin (IL)-1β, IL-6, keratinocyte-derived cytokine (KC) and IL-10 in lung homogenate were increased by pneumonia and, to a lesser extent, by MV." (PMID 24731244, 2014). "Previous studies, in fact, reported the correlation between IL-1β and IL-6 up-regulation and some clinical and radiological findings, such as pneumonia and ARDS, both in experimental animal models and in children with naturally acquired seasonal influenza A." (PMID 23737648, 2013). "In this study the observed levels of IL-1β in the children with PFAPA were low but elevated in comparison to children with pneumonia." (PMID 24134207, 2013). "• At the time of HAP diagnosis, TNF-α, IL-1β, IL-6, IL-8, IL-10 and E-selectin were significantly increased in pneumonia patients with subsequent septic shock compared to patients without subsequent septic shock." (PMID 16280065, 2005). "In the pneumonia group with subsequent septic shock, levels of IL-1β, IL-6, IL-8 and IL-10 were significantly increased before the onset of septic shock compared to patients without subsequent septic shock." (PMID 16280065, 2005). "Relative to controls, cytokines that were significantly elevated in the pneumonia cohort at 24 and/or 48 h after inoculation (evolution phase) were IL‐1β, IL‐6, IL‐15, IL‐16, IL‐17a, IP‐10, MCP‐1, MIP‐1β, and TARC; IL‐5 was significantly elevated at 168 h (resolution phase)." (PMID 40947770, 2025). "In our opinion, this is the first study to identify SNPs in antioxidant (SOD1, CAT, GPX1, NOS, HMOX1, and NQO1) and immunological (IL-1α, IL1B, IL6, TNF-α, IL10, LFA-1, CR2, IL17, IL13, DEFB123, SCART1, and ICAM1) genes as potential suspects for pneumonia resistance/susceptibility in Barki ewes." (PMID 40221769, 2025). "Moreover, LAA treatment reduced ASC, pro-caspase-1, caspase-1 p20, pro-IL-1β, mature-IL-1β, and IL-18 activation in the lungs of pneumonia mice in comparison with S. aureus-treated mice." (PMID 38803378, 2024). "In acute pneumonia, the activation of neutrophils, which act as first responders, results in the release of autocrine cytokines and chemokines such as IL-8, IL-4, IL-6, IL-10, IL-1β, transforming growth factor (TGF)-β, and TNF-α, among others." (PMID 38251391, 2024). "Of the 18 cytokines tested, only IL-6 and IL-1b secretion significantly increased on bilateral sides of HAE during the early stage of pneumonia-derived CVB4 infection, while multiple cytokine secretions significantly increased in HFMD-derived CVB4-infected HAE." (PMID 37725516, 2023). "PVL is an important virulence factor for the induction of apoptosis, acting on NLRP3 to induce macrophage death and IL-1β secretion during the course of pneumonia disease; PVL induces the release of the apoptotic proteins cytochrome c and Smac/DIABLO in mitochondria." (PMID 35878202, 2022). "In this report, the naïve mock vaccinated group demonstrated at necropsy elevated neutrophil levels in BALF, enhanced microscopic pneumonia and proinflammatory lung cytokine profile, including IL-1β, IL-6 and IL-8, compared to both NA2 VLPs and QWIV group of animals." (PMID 35874791, 2022). "Activated macrophages represented the primary source of IL-1β during acute inflammation, and blocking their activation or directly antagonizing IL-1β contributed to reducing tissue inflammation in experimental models of pneumoniae." (PMID 35682923, 2022). "Finally, we proved that pretreatment with ATP combined with IFN-γ was safe and effective in a mouse model of acute pneumonia as evidenced by the significant reduction in alveolar inflammatory cell infiltration and reduced IL-1β and TNF-α levels." (PMID 36260750, 2022).
pneumonia (continued). "In in vivo models using mice with pneumonia induced by C. albicans, there was a reduction in the pro-inflammatory mediators IL-1β and TNF-α, as well as a decrease in the recruitment of leukocytes and neutrophils, when inhalable nanoemulsions containing EO of M. alternifolia were administered." (PMID 34683994, 2021). "In conclusion, we found that the upregulation of the NLRP3 inflammasome was associated with MRSA infection secondary to IAV, but that MRSA superinfection resulted in a decrease in the expression of IL‐1β someway, by which impair the host immunity and lead to aggravated pneumonia." (PMID 32697385, 2020). "Therefore, we infer that superinfection with MRSA reduces expression of IL‐1β someway, and decreased expression of IL‐1β impairs the host immunity and leads to aggravated pneumonia." (PMID 32697385, 2020). "However, IL-6, IL-1β, and IL-8 expression levels in severe pneumonia patients were increased, and the levels of IL-6 showed the greatest increase." (PMID 33065551, 2020). "Further studies also indicated that neutrophils are the major source of IL-1β in a Streptococcus pneumoniae corneal infection model and a relevant source of IL-1β in response to acute Pseudomonas aeruginosa infection during acute pneumonia and peritonitis." (PMID 29515581, 2018). "We demonstrate here that neutrophils are also the major P2X7R-expressing cells in the cornea, and showed by adoptive transfer studies that neutrophil P2X7R is required for IL-1β processing in vivo, and for optimal bacterial clearance during S. pneumoniae corneal infection." (PMID 26877061, 2016). "In patients with severe pneumonia, the IL-6 levels were positively associated with high levels of leukocytes while the levels of TNF and IL-1β were associated with monocytes, possibly related to the recruitment and differentiation of macrophages at the site of inflammation." (PMID 27905908, 2016). "IL-1β is associated with severity of infection, IL-6 reflects the severity of stress, and TNF-α may be a marker of pneumonia severity." (PMID 25815231, 2015). "Moreover, STAT3-dependent IL-1β expression in cDCs at least partially explains the IL-21-mediated pathologic response occurring during infection with pneumonia virus of mice." (PMID 26269257, 2015). "In acute pneumonia, IκBα dose-dependently decreased lung injury, improving arterial oxygenation and lung static compliance, reducing alveolar protein leak and histologic injury, and decreasing alveolar IL-1β concentrations." (PMID 23622108, 2013). "Using PCR-DNA sequence verdicts, the IL-1α (356-bp), IL-1β (423-bp), IL-6 (384-bp), TNFα (490-bp), IL-10 (306-bp), IFN-γ (321-bp), PRDX6 (434-bp), ATG7 (416-bp), NDUFS6 (405-bp), and NOX4 (396-bp) genes were found to have different SNPs in the amplified DNA bases linked to pneumonia." (PMID 40711280, 2025). "IL-33 provides protection against pneumonia-induced acute lung injury, potentially mediated through increased eosinophilia and lower neutrophil recruitment, while the role of IL-1α (in comparison to IL-1β) are poorly understood, but likely act through liver-dependent mechanisms." (PMID 36829255, 2023). "Several iridoids were found to alleviate inflammatory response in A549 cells by reducing the release of proinflammatory cytokine IL-1β and IL-8, as well as increasing the expression of anti-inflammatory cytokine IL-10, which indicated that they may have therapeutic potential for pneumonia." (PMID 37764389, 2023). "However, in several models of pneumonia, IL-1β, in fact, contributes to P. aeruginosa infection." (PMID 33302964, 2020). "Mechanisms of tissue injury in SARS-CoV-2-induced pneumonia share some aspects with influenza virus infection, but IL-1β seems to play more important roles along with CCL2 and impaired type I interferon signaling might be associated with delayed virus clearance and disease severity." (PMID 33062077, 2020).
pneumonia (continued). "Our investigation used a PCR-DNA-sequencing procedure to illustrate the difference in immunological (IL-1α, IL1B, IL6, TNF-α, IL10, and IFN-γ) and antioxidant (PRDX6, ATG7, NDUFS6, and NOX4) genes in calves with pneumonia and healthy calves." (PMID 40711280, 2025). "The genes IL-1α, IL1B, IL6, TNF-α, IL10, IFN-γ, and NOX4 had significantly greater gene expression levels in pneumonia-affected calves compared to the CON group." (PMID 40711280, 2025). "In burn‐ALI mice with secondary pneumonia, CuMPBA restored lung architecture, suppress TNF‐α/IL‐1β/IL‐6 levels, and modulated inflammatory pathways by activating Nrf2 while inhibiting NF‐κB." (PMID 40956292, 2025). "The most significant elevation of plasma proinflammatory cytokines (IL-6, IL-1β, MCP-1, IP-10 and TNF-α) at 5 dpi were also detected in Subjects 03 and/or 04, suggesting more severe pneumonia-induced systemic inflammation." (PMID 41157643, 2025). "In our study, we performed a correlation analysis in the group of patients with HIV and pneumonia, evaluating the cytokines IL-6, IL-17A, MCP1/CCL2, PAI1, IL-1β, and VEGF/VPF in relation to key parameters of lung function." (PMID 38251391, 2024). "The ELISA results measuring the concentrations of TNF-α and IL-1β in the BALF revealed a significant increase in the production and release of these cytokines in LPS-induced pneumonia, leading to a heightened inflammatory response in the lung tissues." (PMID 37446875, 2023). "In our study, the serum levels of TNF‐α, IL‐1β, and NLRP3 were significantly elevated in children with KD and pneumonia compared with healthy subjects." (PMID 37773705, 2023). "Seven hub genes, IL4, IL6, CSF2, IFNG, IL1B, TNF and IL17A, were responsible for Experimental Lung Inflammation, Pneumonitis, Pneumonia and Lobar Pneumonia." (PMID 36989283, 2023). "Multiple pro-inflammatory cytokines have been detected to have a certain amount of expression in the pneumonia model, such as TNF-α, IFN-γ, IL-1β, and IL-6." (PMID 36707501, 2023). "In this study, we analyzed the levels of serum IL‐6, IL‐8, IL‐10, IL‐1β, sIL‐2R and TNF‐α in children with pneumonia." (PMID 37142438, 2023). "In a M. pneumoniae pneumonia mouse model, TFCO significantly reduced the lung damage, suppressed IL-1β, IL-6, and TNF-α production, and curbed TLR2 activation triggered by M. pneumoniae." (PMID 37894556, 2023). "In our study, phillyrin downregulated IL-1β production and inflammatory responses in BALF from H1N1-induced pneumonia mice." (PMID 37957672, 2023). "However, in the progression of pneumonia, cytokine storms caused by excessive responses of M1-type macrophages and the secretion of excessive cytokines such as tumor necrosis factor-alpha (TNF-α), interleukin-1 beta (IL-1β), interleukin-6 (IL-6), and other factors can be fatal." (PMID 37176064, 2023). "MRSA-induced pneumonia feces recipients exhibited a trend toward higher bronchoalveolar lavage fluid (BALF) TNF-α, IL-6, IL-1β, CXCl-1, MCP-1 levels, and W/D ratio." (PMID 37823635, 2023). "We collected sera from healthy physical examiners, children with KD, and children with pneumonia and measured the levels of TNF‐α, IL‐1β, NLRP3, and LL‐37 in serum." (PMID 37773705, 2023). "Enzyme‐linked immunosorbent assay (ELISA) was used to detect the levels of tumor necrosis factor‐α (TNF‐α), interleukin (IL)‐1β, NLRP3, and LL‐37 in the sera of healthy subjects, children with KD, and children with pneumonia." (PMID 37773705, 2023). "Pre-existing T. spiralis infection decreased lung neutrophil recruitment, inflammatory mediator IL-1β and IL-6 expression and chemokine CXCL1 and CXCL2 release during P. aeruginosa- pneumonia." (PMID 35500031, 2022). "Elevated concentrations of both pro- and anti-inflammatory plasma cytokines were observed in the pneumonia group, including G-CSF, HGF, IL-1b, IL-1RA, IL-2, IL-2Ra, IL-6, IL-10, IL-18, IP-10, monocyte chemoattractant protein-3 (MCP-3), and TNF-α." (PMID 36119044, 2022).
pneumonia (continued). "It has a therapeutic impact on pneumonia model rats by reducing B lymphocytes, CD8+ ratio, and elevated levels of IL-1α, IL-1β, IL-2, IL-10, TNF-α, IFN-α, IFN-γ, IgM, IgG, CD4+/CD8+, and NK cells." (PMID 36388945, 2022). "Then, the expressions of 25-OH-VD, VDR, TGFβ, IL-2, IFN-γ, TNFα, IL-1β, Ca2+, PCT, CRP, and IL-6 in mild pneumonia, severe pneumonia, and healthy controls were determined using qRT-PCR, western blot, ELISA, and calcium colorimetry assay." (PMID 34643152, 2021). "After treatment with Bm (75, 150, and 300 μg/kg), TNF-α, IL-6, IL-1β, and PEG2 levels in Kp-induced pneumonia mice exhibited a downward trend in a dose-dependent manner." (PMID 34017253, 2021). "Specifically, three targets including IL-1β, IL-6, and TNF-α have been reported to be related to pneumonia, which were further validated in vivo." (PMID 32625244, 2020). "In vivo data also indicated that both pN11R and pG31P significantly relieved LPS-induced pneumonia in mice through decreasing the expression of TNF-α, CXCL8, and IL-1β, and inhibiting neutrophil influx into the lung." (PMID 31988368, 2020). "CU-CPT9a strongly reduced (70–100%) the production of IL-12p70 and IL-1β after challenging the monocytes with the Gram-positive species GBS, S. aureus, and S. pneumonia." (PMID 31214180, 2019). "The levels of the pro-inflammatory cytokines/chemokines including TNF-α, IL-1β, IL-6, MCP-1 and KC were significantly higher in the HNP+ pneumonia mice under HP ventilation than other groups." (PMID 30268129, 2018). "We next assessed the contribution of IL-1β, CXCL1, CCL2, and CCL7 to the recruitment of neutrophils during S. pneumoniae pneumonia using specific neutralizing Abs administered intranasally." (PMID 25948816, 2015). "Levels of IL-1β were low but detectable in children with PFAPA, but undetectable in children with pneumonia." (PMID 24134207, 2013). "The levels of several pro- and anti-inflammatory cytokines (including IL-1β, IL-6, IL-10, IL-13, G-CSF and TNFα) were examined in BAL fluid 24 hours after the onset of pneumonia in both genotypes." (PMID 23145105, 2012). "In fact, these viruses markedly induced the expressions of pro-inflammatory cytokines and chemokines including IL6, IL1α, IL1β, TNFα, IFNγ and CCL5 in the lungs, resulting in severe pneumonia." (PMID 21826229, 2011). "In HAP patients with subsequent septic shock, IL-1β, IL-6, IL-8 and IL-10 were superior predictive markers than TNF-α, E-selectin and conventional laboratory values and scores at the time of pneumonia diagnosis." (PMID 16280065, 2005). "Additionally, the levels of the inflammatory cytokines IL-1β, IL-6, and TNF-α in bronchoalveolar lavage fluid (BALF) and plasma were significantly elevated in mice receiving FMT from patients with pneumonia." (PMID 40736248, 2025). "In sepsis and pneumonia models, prophylactic vaccination produced significant reductions in lung bacterial colonization and the levels of pro-inflammatory cytokines (IL-6, TNF-α and IL-1β), resulting in 100% survival over 14 days." (PMID 40076637, 2025). "A low level of IL-1β in the lungs of two – hit mice was reflected by a lower number of recruited neutrophils early after pneumonia induction in comparison to non-septic mice, which is likely another mechanism impairing the clearance of pathogens." (PMID 40202049, 2025). "The importance of IL-1α as mediator of lung inflammation has recently been shown in the randomized clinical trial SAVE-MORE; patients with pneumonia by the novel coronavirus SARS-CoV-2 were treated for 10 days with anakinra which is blocking the biological action of both IL-1α and IL-1β." (PMID 37680472, 2023). "HUC-MSC treatment reduced IL-1β and TNF-α levels in acute pneumonia mice." (PMID 36260750, 2022). "Pneumonia is characterized by the production of inflammation-related cytokines and chemokines throughout the body, especially in the lungs, including TNF- α, IFN- γ, IL-6 and IL-1β which are controlled by TLR4/NF-κB signaling pathway." (PMID 36530439, 2022).
pneumonia (continued). "Meanwhile, the results of molecular docking also exposed the active ingredients of YPFG could tack a part in modulating the progression of pneumonia via MMP9, CCL2, IL-1B, IL-6, CXCL8, and TNF." (PMID 36285159, 2022). "Furthermore, H1N1 infection caused significant elevation of mRNA levels by up to 3-6-fold for IL-1β, IL-6, and TNF-α, reinforcing the successful establishment of virus-induced pneumonia." (PMID 32901688, 2020). "In addition, significant increase was observed in the TNF-α, IL-6, IL-1β, and MPO in the BALF and lung tissue samples collected from the KP-infected pneumonia mice, which were reversed by anemoside B4." (PMID 32625244, 2020). "Pneumonia resulted in increased pulmonary concentrations and gene expression of both IL-8 and IL-1β, but not TNF-α." (PMID 30082877, 2018). "In the present study, the cytokines, TNF, IL-1β, IL-6, IL-8, IL-12p70, IFN-γ, IL-17A, IL-10 and IL-5, were detected in the serum of children with pneumonia and severe pneumonia at hospital admission, and IL-6 was the only cytokine associated with disease severity." (PMID 27905908, 2016). "Systemically, pneumonia caused modest inflammation, with increased plasma levels of IL-6, but not of TNF–α, IL-1β and CINC3 when compared to non-infected controls (p<0.05)." (PMID 23717435, 2013). "Our finding that pro-inflammatory gene expression is stronger in BALB/c mice is in line with several previous studies that compared C67Bl/6 and BALB/c mice: After infection with mcyoplasma pneumonia, the BAL levels of CXCL1, MIP-1α, MCP-1, IL-1b and IL-6 were higher in BALB/c mice." (PMID 22848503, 2012). "At the 'diagnosis of pneumonia', TNF-α, IL-1β, IL-6, IL-8, IL-10 and E-selectin were significantly increased in those patients who had subsequent septic shock, compared to patients with pneumonia without subsequent septic shock." (PMID 16280065, 2005). "The cytokines IL-1β, IL-6, and TNF-α, which are key indicators of inflammation, were found to be elevated in the model control group compared to the control group, with extremely significant statistical differences, confirming the inflammatory nature of the LPS-induced pneumonia model." (PMID 40271073, 2025). "In this study, the results showed that IL-1β, IL-6 and TNF-a in control group were lower than those of the model control group, and there were extremely significant statistical differences (p < 0.001), indicating that LPS-induced zebrafish pneumonia models elevated inflammatory factors." (PMID 40271073, 2025). "Thus, we tested the levels of IL-6, TNF-α, and IL-1β in culture supernatants from macrophages, serum and BALF, and the results showed that LAA reduced the levels of IL-6, TNF-α, and IL-1β in culture supernatants from S. aureus-induced macrophages and serum and BALF of pneumonia mice." (PMID 38803378, 2024). "Moreover, the elevation of TNF‐α, IL‐1β, and NLRP3 was more pronounced in KD than in children with pneumonia, which may be related to the storm of inflammatory factors triggered by immune imbalance in KD." (PMID 37773705, 2023). "While LPS-induced acute pneumonia caused an increase in cytokine/chemokine mRNA expression, including that of IL-1β, -6, TNF-α, MCP-1, TauCl treatment attenuated IL-6, and TNF-alpha expression, but not IL-1β and MCP-1." (PMID 35448536, 2022). "Measurement of inflammatory cytokine levels using ELISA showed that IL-1β, IL-6, TNF-α, IL-2, IL-8, IL-12, and IFN-γ levels were significantly enhanced, while IL-10 levels were significantly reduced in the lung homogenates of Spn-induced pneumonia mice, compared with the normal mice." (PMID 32460745, 2020). "NLRC4 activation during Gram-negative bacterial (K. pneumoniae, P. aeruginosa) pneumonia proves beneficial to the host via producing IL-1β, IL-17A, and neutrophil chemoattractants (keratinocyte cell-derived chemokines, MIP-2, and LPS-induced CXC chemokines) in the lungs." (PMID 32849610, 2020).